TERT (telomerase reverse transcriptase)
Diseases named in the same sentence as TERT in open-access papers (continued):
Sharing a sentence is not in itself a finding about the gene and the disease.
glioblastoma (continued). "First, we evaluated the accuracy of DeepMEL2 and other methods to predict functional changes across the TERT promoter, by comparing the predictions to a previously published saturation mutagenesis screen performed in a glioblastoma cell line." (PMID 33832990, 2021). "The aim of this systematic review is to provide an overview of the available data concerning TERT alterations and glioblastoma in terms of incidence, physiopathological understanding, and potential therapeutic implications." (PMID 33800183, 2021). "For a diagnosis of “Glioblastoma, IDH-wildtype” the novel WHO CNS5 incorporates 3 genetic parameters (TERT promoter mutation, EGFR gene amplification, combined gain of entire chromosome 7 and loss of entire chromosome 10) as criteria." (PMID 35008238, 2021). "As a consequence, TERT transcription and TERT protein levels were reduced resulting in human glioblastoma cell senescence." (PMID 34199901, 2021). "Among them, the alterations in the promoter region of the telomerase reverse transcriptase (TERTp) gene are highly recurrent and occur in 70% to 80% of all glioblastomas, including glioblastoma IDH wild type and glioblastoma IDH mutated." (PMID 33800183, 2021). "Previous studies have shown that patients with IDH-wildtype TERTp-mutant glioblastoma have a significantly shorter progression free and overall survival compared to those with TERT-wildtype status." (PMID 34490493, 2021). "The histopathological diagnosis confirmed the nature of glioblastoma grade IV, IDH wild type, TERT promoter mutated, and MGMT wild type." (PMID 33716935, 2021). "GABPA is central to TERT expression in glioblastoma as it had been shown that the knockdown of GABPA significantly reduced mutant promoter activity without affecting wild-type promoter activity." (PMID 33547950, 2021). "Recently, Liu and co-workers reported that the p52 transcription factor driven by noncanonical NF-κB signaling cooperates with ETS1/2 to regulate TERT expression specifically from the C250T-mutant promoter in glioblastoma." (PMID 31957804, 2020). "With this cross‐study analysis based on large recent cohorts of glioblastoma patients, we provide evidence for a prognostic role of DDR genes including DDR methylome and TERT promoter mutation status." (PMID 32991787, 2020). "Our recent study investigated on a more recent cohort from our institution demonstrated that TERT promoter wildtype glioblastoma, IDH wildtype harbored frequent PI3K pathway mutations as compared to the TERT promoter mutant counterpart." (PMID 31036078, 2019). "Previous studies in BRAF wild-type glioblastoma models have already demonstrated a central role of GABPA in activation of the mutant TERT promoter." (PMID 31391125, 2019). "In our series, a mistake almost made was the diagnosis of a molecular glioblastoma in a fossa posterior tumor in a young patient with histological characteristics of a medulloblastoma (7+/10-, TERT +)." (PMID 30470264, 2018). "Here, the authors present a genetic landscape of TERTpWT-IDHWT glioblastoma, identifying a telomerase-positive subgroup driven by TERT-structural rearrangements and an ALT-positive subgroup with mutations in ATRX or SMARCAL1." (PMID 29802247, 2018). "More importantly, the silencing of TERT gene expression significantly suppressed the proliferation of glioblastoma cells." (PMID 28420995, 2017). "As will be discussed in greater detail later, it was recently found that Hh signaling upregulates telomeric activity by increasing TERT expression in glioblastoma multiforme (GBM)." (PMID 26988232, 2016). "When addressing primary glioblastomas, which are believed to arise de novo, ALT is less frequently observed and TERT promoter mutations start to become very frequent; they are the main mechanism for telomere maintenance and associated to a worse prognosis." (PMID 27657132, 2016).
glioblastoma (continued). "Telomerase reverse transcriptase (TERT) activity is up-regulated in several types of tumors including glioblastoma (GBM)." (PMID 26143636, 2015). "The high frequency of TERT promoter mutations in primary glioblastomas and an inverse association between IDH and TERT promoter mutations in astrocytomas and secondary glioblastomas suggests that those patterns of mutations represent astrocytic progression." (PMID 25797251, 2015). "We observed positive association between TERT promoter and IDH mutations in oligodendroglial tumors (OR = 26.3; 95% CI 2.5–250.2) and inverse association in primary glioblastomas (OR = 0.13; 95% CI 0.03–0.58)." (PMID 25797251, 2015). "In primary glioblastomas the frequency of IDH mutations was low (8/165, 5%) and showed an inverse correlation (OR 0.13; 95% CI 0.03 – 0.58; P = 0.002) with TERT promoter mutations (132/165; 80%)." (PMID 25797251, 2015). "In glioblastomas, median OS is significantly lower than in other subtypes, and this factor could be indirectly related to the transcriptomic activity of the TERT identified in our classifier." (PMID 40867242, 2025). "The mutation status of the 21 patients with glioblastoma was as follows: all 21 had isocitrate dehydrogenase (IDH)-wildtype; 11 had a telomerase reverse transcriptase (TERT) promoter C228T mutation, and 10 had an O6-methylguanine-DNA methyltransferase (MGMT) methylation." (PMID 40866807, 2025). "The latest WHO classification adopts a multi-layer integrated approach to defining glioblastoma, integrating histological features with molecular signatures: IDH-1 mutation, EGFR amplification, TERT promoter mutations, and the combined gain of chromosome 7 and loss of chromosome 10." (PMID 41008823, 2025). "Molecular analysis confirmed IDH1/2-wildtype status, absence of 1p/19q codeletion, and presence of a TERT promoter mutation, consistent with glioblastoma IDH-wildtype per the WHO CNS5 criteria." (PMID 40417325, 2025). "All samples had molecular features of glioblastoma, including TERT promoter mutation (C228T), lack of IDH1 R132H mutation (confirmed by immunohistochemistry in all cases, and additionally by sequencing in two cases), and gain of chromosome 7." (PMID 38650010, 2024). "Contrary to prior findings that TERT mutations are linked with poor prognosis in glioblastoma, our analysis did not indicate a detrimental impact of TERT mutations on survival in such cases." (PMID 38982347, 2024). "The finding of a TERT promoter mutation, the alterations in the CNV profile, and a high confidence classification gave sufficient evidence for the diagnosis high-grade glioma/glioblastoma." (PMID 39225924, 2024). "Additionally, the identification of IDH mutations has been leveraged to guide prognosis, while the definition of glioblastoma has been refined through the analysis of TERT promoter, EGFR amplification, gain of chromosome 7, and loss of chromosome 10." (PMID 38553633, 2024). "Tumors with a TERT mutation and/or EGFR amplification were reclassified as glioblastoma." (PMID 38672254, 2024). "In a double-blind, placebo-controlled phase 2 study, autologous DC vaccine loaded with glioblastoma-stem-cell-like lines (GSC) prolonged OS in the IDH1-wildtype TERT-mutant and B7-H4 low expression newly-diagnosed GBM patients, with increasing levels of plasma CCL22 and IFN-γ." (PMID 37444531, 2023).
glioblastoma (continued). "However, mutations in the TERT promoter cause destabilization of G-quadruplex structures and TRF2 displacement resulting in telomerase overexpression in glioblastoma multiforme cells." (PMID 38033865, 2023). "These tumors generally occur at a younger age compared to conventional glioblastomas and mostly lack the molecular hallmarks of conventional glioblastoma including EGFR amplification, trisomy 7 plus monosomy 10, TERT promoter mutation, and CDKN2A/B homozygous deletion." (PMID 38079020, 2023). "The present study demonstrates that adding the TERT promoter mutation status to standard markers, as suggested in the literature, results in a precise molecularly directed classification with IDH-WT/ TERT -mutant tumors representing the primary glioblastoma group." (PMID 34558656, 2022). "Based on a multicenter cohort of 466 IDH-wildtype glioblastomas (including 396 with and 70 patients without TERT promotor mutations), we found that TERT promotor mutations were neither associated with progression-free survival nor overall survival." (PMID 36325373, 2022). "Furthermore, glioblastoma patients with wild-type EGFR had longer survival with wild-type TERT than patients with wild-type EGFR and mutated TERT." (PMID 35806478, 2022). "Patients with TERT mutated glioblastomas who were treated with radiation doses < 45 Gy (HR 3.019, p = 0.0010) but not those treated with ≥ 45 Gy exhibited worse OS compared to those without TERT mutations." (PMID 36380219, 2022). "Indeed, glioblastoma cells knocked-out of GABPB1, the GABPA partner required for activation of the mutated TERT promoter, was shown to undergo telomere shortening, senescence or apoptosis and eventual loss of tumorigenesis." (PMID 35549739, 2022). "Conventional radiology does not identify specific features related to TERT mutations other than those related to oligodendrogliomas or glioblastomas." (PMID 35693015, 2022). "Inhibition of TERT effectively reduces angiogenesis in glioblastoma (George, Banik & Ray, 2009)." (PMID 36299510, 2022). "Indeed, following stable GABPB1 knockdown, glioblastoma cells carrying C228T or C250T TERT promoters undergo diminished TERT/telomerase expression, progressive telomere erosion and eventual loss of tumorigenic potential." (PMID 36713366, 2022). "Additionally, one of those cases (glioblastoma) was found to have DNA-based mutations (PTEN, TERT-promoter, and FGRF4)." (PMID 35295612, 2022). "Furthermore, higher grade, IDH-wild type, non-1p19q codeletion, ATRX-wild type, MGMT unmethylated, TERT mutant, and glioblastoma were correlated with a higher CRGRS." (PMID 36267281, 2022). "In addition, diffuse astrocytoma, if accompanied by microvascular proliferation or necrosis or TERT promoter mutation or EGFR gene amplification or + 7/-10 chromosome copy number changes, will also be included in glioblastoma, IDH wild type category." (PMID 35241019, 2022). "Data from the NOA-04 trial demonstrated the positive predictive value of MGMT promotor methylation in IDHwt astrocytomas WHO grade III but did not test for molecular features of glioblastoma like TERT promotor mutation." (PMID 34902093, 2022). "Among the nine pathways that have the FDR (false discovery rate) of < 0.05 (upper), four are directly related to glioblastoma, the rest include general cancer pathways, TERT-related pathways, all of which are determinate factors of glioblastoma malignant behavior." (PMID 35521558, 2022).
glioblastoma (continued). "Only 2/6 of the NF1-associated glioblastomas from our study had the combination of trisomy 7 and monosomy 10, and none harbored TERT promoter mutation or EGFR amplification." (PMID 35945463, 2022). "TERT mRNA positive cells were observed in a second glioblastoma case with a TERTp duplication." (PMID 36114166, 2022). "Survival analysis in patients with primary glioblastomas did not reveal any effect of the TERT promoter mutations." (PMID 34558656, 2022). "Moreover, the presence of TERT promoter mutations, EGFR alterations, or a combination of chromosome 7 gain and 10 loss upgrade IDH-wildtype astrocytoma to glioblastoma." (PMID 34638714, 2021). "Additionally, TERT promoter mutations, EGFR alterations, and 7+/10− upgrade IDH-wildtype astrocytomas to glioblastomas." (PMID 34638714, 2021). "None of the spinal glioblastomas had a TERT promoter mutation, while typical copy-number alterations such as CDKN2A/B deletion or CDK4 amplification were observed in some tumors." (PMID 34193285, 2021). "For example, EGFR alterations and TERT promoter mutations are associated with poor prognosis, whereas IDH mutations and MGMT promoter methylation are associated with favorable prognosis in glioblastoma patients." (PMID 34732244, 2021). "None of the glioblastomas in our cohort had a TERT promoter mutation, which is common in the supratentorial counterparts." (PMID 34193285, 2021). "Finally, TERT promoter mutation is one of the three genetic parameters that WHO CNS5 uses to upgrade astrocytoma, IDH-wildtype to glioblastoma, IDH-wildtype." (PMID 34638714, 2021). "We present that TERT is mainly expressed in primary glioblastomas." (PMID 34194624, 2021). "The FGFR3 glioblastoma cases exhibited the most common mutations found in IDH-wild-type glioblastoma, with CDKN2A homozygous loss in all cases, followed by PTEN mutations with LOH and CDKN2B homozygous loss, in three cases, and TERT c.124C>T promoter mutation in two cases." (PMID 33853673, 2021). "Twenty‐eight glioblastoma 5'‐cytosine‐phosphat‐guanine‐3' (CpGs) from 17 DDR genes negatively correlated with expression and were used together with telomerase reverse transcriptase (TERT) promoter mutations in further analysis." (PMID 32991787, 2020). "As described recently, “adult-type” grade II diffuse astrocytomas with no IDH mutations often harbor EGFR amplification, TERT promoter mutations or combined whole chromosome 7 gain and whole chromosome 10 loss and have glioblastoma-like behavior." (PMID 32771057, 2020). "Hypomethylation of DDR genes and TERT promoter mutations is associated with worse tumor prognosis, dependent on the methylation cluster and MGMT promoter methylation status in IDH wild‐type glioblastoma." (PMID 32991787, 2020). "Therefore, the interactions between PIK3R1 mutation, TERT promoter mutation and PIK3CA mutation in adult glioblastoma clinical characteristics remain to be determined." (PMID 31036078, 2019). "Since many types of human cancer lack any TERT promoter mutations, and even in bladder cancer and glioblastoma, up to 30% of the tumors are negative for a mutation, other telomerase-related markers are apparently required for those patients." (PMID 31285550, 2019). "In human glioblastoma cells, transcription of the C250T mutant telomerase (TERT) promoter was reactivated by p52 cooperating with the E-twenty-six family of transcription factors, promoting further regulation of TERT transcription and tumorigenicity." (PMID 31552177, 2019). "Whilst TERT promoter mutations are also seen in a proportion of IDH-wildtype glioblastomas and other tumours, they are generally not seen in IDH-mutant astrocytomas." (PMID 29098416, 2018). "Activation of noncanonical NF-κB, but not canonical NF-κB, was shown to increase TERT expression in glioblastoma cells containing one of these hotspot mutations (C250T)." (PMID 29874793, 2018).
glioblastoma (continued). "Nonetheless, it may be of interest that TERT mRNA expression was elevated in RELA fusion-positive ST-EPNs, to an extent which far exceeded that in glioblastomas with TERT promoter mutations." (PMID 30514397, 2018). "However, about 20% of glioblastomas lack alterations in the TERT promoter and IDH genes and are defined as TERTpWT-IDHWT; they apparently do not seem to possess the defined molecular mechanisms of telomere maintenance." (PMID 30279357, 2018). "Glioblastoma can be classified based on IDH and TERT promoter mutations, but ~20% of glioblastoma do not have these mutations (TERTpWT-IDHWT glioblastoma)." (PMID 29802247, 2018). "Interestingly, in the context of this study, a novel mechanism of telomere activation in glioblastomas was identified, operating via chromosomal rearrangements upstream of TERT." (PMID 30279357, 2018). "We also observed the down-regulation of TERT gene had inhibited the proliferation of the glioblastoma cells and we envisioned that such engineered approach might serve as a new and effective way for combating glioblastoma gene therapy." (PMID 28420995, 2017). "For genetic therapy of glioblastoma, we designed siRNA sequences specifically targeting TERT gene." (PMID 28420995, 2017). "In addition, we also analyzed the relationship between TERT promoter status and patient survival for other histological types including oligodendroglioma, oligoastrocytoma and glioblastoma." (PMID 26556853, 2016). "In a previous study of glioblastoma samples, none of the studied SNPs in the TERT (5p15.33) region were associated with nearby DNA methylation." (PMID 27780202, 2016). "We found that TERT SNPs rs2736100 and rs10069690 located in intron 2 and 4 respectively were associated with increased risk of glioblastoma, but not for oligodendroglioma." (PMID 26143636, 2015). "TERT mutations are mutually exclusive with ATRX (alpha thalassemia mental retardation syndrome X linked) mutations, which are instead seen in the majority of WHO grade II-III astrocytomas and secondary glioblastomas." (PMID 25943885, 2015). "In survival analysis in patients with primary glioblastomas we did not observe any effect of the TERT promoter mutations." (PMID 25797251, 2015). "An important mutation that is missed in our exome-centric analysis is an upregulating mutation in the promoter of the telomerase reverse transcriptase (TERT), observed in 58% to 84% of primary glioblastomas, suggesting that telomere lengthening plays an important role in tumor growth." (PMID 25484917, 2014). "However, larger scale studies published by the RANO resect team show that absence of TERT promoter mutation does not confer a survival advantage in glioblastoma." (PMID 41212363, 2025). "The higher proportion of TERT promotor mutations (68.3%) and EGFRvIII expression (47.9%) in those IDH-wt astrocytoma that where tested, strongly suggests that a substantial number of these cases would be reclassified as “molecular IDH-wt glioblastoma CNS WHO grade 4” according to WHO 2021 criteria." (PMID 41466163, 2025). "Unlike oligodendrogliomas and glioblastomas, which both frequently feature mutations in the promoter region of TERT to maintain telomere length, IDH-mutant astrocytomas frequently have mutations in ATRX, promoting an alternative lengthening of telomere (ALT) phenotype." (PMID 39012509, 2024). "Diagnosis of IDH-wild-type glioblastoma within the context of an IDH-wild-type diffuse and astrocytic glioma is dependent on the presence of several criteria—microvascular proliferation, necrosis, TERT promoter mutation, EGFR gene amplification, or +7/−10 chromosome copy number changes." (PMID 38891962, 2024). "Additionally, three patients were diagnosed with glioblastoma on a methylation array, of whom one had failed TERT testing and two were non-TERT-mutated." (PMID 38672254, 2024).